AR (androgen receptor)
Diseases named in the same sentence as AR in open-access papers (continued):
Sharing a sentence is not in itself a finding about the gene and the disease.
androgen insensitivity syndrome (continued). "Furthermore, in family 3 we identified a variant in the androgen receptor gene AR (OMIM *313700) that may lead to the androgen insensitivity syndrome (OMIM # 300068) and thus explain the micropenis regardless of MINPP1." (PMID 33168985, 2021). "Androgen insensitivity syndrome (AIS) is a rare X-linked disorder of sex development, occurs in 1 out of 20,000 births, and is caused by mutations in the androgen receptor (AR) gene." (PMID 33863387, 2021). "Mutations in AR failing to activate its target genes result in hereditary disorders such as androgen insensitivity syndrome (AIS) or testicular feminization (Tfm) mutation in human." (PMID 34869354, 2021). "Interestingly, several human AR mutations associated with oligospermia and androgen insensitivity syndrome map to a conserved amino acid just downstream of the primary SUMOylation motif in AR and they attenuate the AR SUMOylation, implying clinical relevance of our findings." (PMID 30770815, 2019). "Androgen insensitivity syndrome (AIS) is caused by a mutation in the gene encoding the AR (Xq11–q12)." (PMID 31731497, 2019). "In horses three mutations of androgen receptor (AR) gene, responsible for androgen insensitivity syndrome (AIS), were reported." (PMID 30338045, 2018). "AR mutations cause androgen insensitivity syndrome (AIS), possibly the most frequently described hormone insensitivity syndrome." (PMID 25999913, 2015). "Furthermore, some single nucleotide polymorphisms (SNP) in the AR gene, resulting in an altered binding with cofactors, have been linked with the androgen insensitivity syndrome (AIS) and could therefore affect androgen action and circulating androgen levels." (PMID 24465978, 2014). "Androgen insensitivity syndrome (AIS) is an X-linked recessive disorder caused by mutations of the androgen receptor (AR)." (PMID 23762728, 2013). "Mutations in the AR gene cause X-linked androgen insensitivity syndrome (AIS) characterized by androgen unresponsiveness, which affects proper male sexual development both at embryogenesis and at puberty." (PMID 21902827, 2011). "Androgen Insensitivity Syndrome (AIS,OMIM: 300068) is an X-linked recessive genetic disorder associated with mutations in androgen receptor (AR) coding genes." (PMID 40352611, 2025). "Furthermore, although the androgen receptor (AR) is the only gene that has been shown so far to be linked to androgen insensitivity syndrome (AIS), the androgen signaling pathway is complex, with over 400 different AR mutations leading to AIS104." (PMID 41173938, 2025). "In vitro studies of genital skin-derived fibroblasts (GSFs) from patients with androgen insensitivity syndrome (AIS) type II and DAAM2 variants showed reduced dihydrotestosterone (DHT)-induced AR activity compared to WT GSFs." (PMID 39337600, 2024). "AR is involved in the development of various diseases, including androgen insensitivity syndrome, spinal muscular atrophy, hypogonadism, and benign prostatic hyperplasia." (PMID 39529201, 2024). "The requirement for AR-mediated gene regulation in male sex development is demonstrated by individuals with androgen insensitivity syndrome." (PMID 39080028, 2024). "Monogenic disorders of androgen synthesis also demonstrate the effects of androgen insufficiency, such as androgen insensitivity syndrome (AIS), caused by AR dysfunction." (PMID 37171897, 2023). "The AR (HGNC: 644) pathogenic variant detection rate ranges from 65% to 95% for patients with complete AIS (CAIS) and 40%-45% for patients with partial androgen insensitivity syndrome (PAIS)." (PMID 36506311, 2022). "As AR has a key role in androgen insensitivity syndrome (AIS), a disease often leading to defects in virilization and infertility, investigating the role of mutations, including the polymorphic GGN/polyG alleles, are of high importance." (PMID 36388907, 2022).
androgen insensitivity syndrome (continued). "We surveyed articles in the PubMed database using the following search terms: androgen receptor*, Sertoli cell*, spermatogonia*, maturation and differentiation*, spermatogenesis*, meiosis*, spermatid* and androgen-insensitive syndrome*." (PMID 35282467, 2022). "This review also includes one disease related to androgen receptor signaling dysfunction named as androgen insensitivity syndrome." (PMID 35282467, 2022). "Surprisingly, we found that the same inactivating mutations introduced in the D-box domain (A596T and S597T), identified in patients with androgen insensitivity syndrome, had a different effect on AR-fl compared to AR-V7." (PMID 35848798, 2022). "We identify novel allosteric surfaces which are compromised in androgen insensitivity syndrome, and reinforced by AR’s oncoprotein cofactor, ERG, and by DNA binding motifs." (PMID 35447082, 2022). "These alterations in AR SUMOylation play significant roles in AR-based diseases, oligospermia, androgen insensitivity syndrome, and recurrent prostate cancer." (PMID 33572160, 2021). "Of those, about 600 were found in androgen insensitivity syndrome (AIS) patients, among which 400 mutations affect the ligand-binding domain (LBD) of the AR protein." (PMID 34357031, 2021). "Androgen action is mediated through the androgen receptor (AR); changes in its structure lead to different clinical phenotypes, ranging from complete androgen insensitivity syndrome (CAIS) to apparently normal males." (PMID 33811609, 2021). "Disruption of AR leads to androgen insensitivity syndrome and partial sex reversal, depending on the degree of disruption." (PMID 34301922, 2021). "Androgen insensitivity syndrome (AIS), manifesting incomplete virilization in 46,XY individuals, is caused mostly by androgen receptor (AR) gene mutations." (PMID 33182400, 2020). "Androgen receptor gene (AR) defects have occasionally been described in patients with a complete or partial androgen insensitivity syndrome (CAIS or PAIS) in whom sex chromosome analysis revealed a 47,XXY karyotype corresponding to a Klinefelter syndrome." (PMID 32155719, 2020). "When AR mutations happen in the germline, the situation is similar, a broad spectrum of functional consequences can result ranging from absence of phenotypic changes to different androgen insensitivity syndromes (AIS)." (PMID 32714315, 2020). "Because AR is expressed in blood cells, this tissue has been demonstrated to be feasible for diagnosing genetic disorders affecting AR, such as androgen insensitivity syndrome." (PMID 31947623, 2020). "Abnormal androgen receptor (AR) genes can cause androgen insensitivity syndrome (AIS), and AIS can be classified into complete androgen insensitivity syndrome (CAIS), partial androgen insensitivity syndrome (PAIS) and mild AIS." (PMID 32345305, 2020). "As the chromosomal sex identified as male with the corresponding 64, XY karyotype with the presence of SRY gene, a 64, XY DSD syndrome and Androgen Insensitivity Syndrome was suspected, leading to the molecular testing of the AR-gene." (PMID 31936796, 2020). "We have now investigated AR homodimerization, hormone-dependent monomerization and nuclear translocation in PC-3 and COS-1 cells, by utilizing mutations associated with the androgen insensitivity syndrome: Pro767Ala, Phe765Leu, Met743Val and Trp742Arg." (PMID 31723170, 2019). "Variants in AR are known causes of androgen insensitivity syndrome (AIS)." (PMID 26980296, 2016). "Androgen insensitivity syndrome (AIS) (online inheritance in man number 300068) is a DSD that is classically characterized as a disorder of hormone action due to a reduced or absent functionality of the androgen receptor (AR) protein encoded by the AR gene." (PMID 27583472, 2016). "At the other end of the spectrum, defects at both pre- and post-receptor levels of the AR signaling axis are involved in partial or complete androgen insensitivity syndromes." (PMID 26876983, 2016).
androgen insensitivity syndrome (continued). "Androgen insensitivity syndrome (AIS), a disorder of sexual development in 46, XY individuals, is caused by loss-of-function mutations in the androgen receptor (AR) gene." (PMID 27267075, 2016). "Genetic defects that alter the function of AR can cause a wide range of abnormalities in male sexual development, and the effects of these defects are collectively referred to as androgen insensitivity syndrome (AIS)." (PMID 25997614, 2015). "46XY individuals with complete androgen insensitivity syndrome (CAIS) lack a functioning androgen receptor, and their tissues are unable to respond to testosterone/DHT." (PMID 24363669, 2013). "Physical examination, karyotype testing and molecular analysis of the androgen receptor were critical in making the correct diagnosis of complete androgen insensitivity syndrome." (PMID 21902827, 2011). "Molecular abnormalities in the androgen receptor gene in individuals of a Brazilian family with clinical features of severe forms of partial androgen insensitivity syndrome were evaluated." (PMID 21645389, 2011). "Tissue-specific knockout of Dicer in mice completely impaired AR function leading to an androgen-insensitivity syndrome." (PMID 21048966, 2010). "AR action is a conditio sine qua non for the normal development and function of the entire male genital tract; conversely, varyingly degrees of impaired AR action from mutation is causative in individuals affected by androgen insensitivity syndrome (AIS)." (PMID 20011049, 2009). "AIS, formerly termed testicular feminization, is an X-linked recessive disorder caused by mutations in the androgen receptor (AR) gene, resulting in incomplete or absent masculinization of the external genitalia in chromosomally male (46,XY) individuals." (PMID 41515635, 2026). "Disruptions in this pathway are associated with androgen insensitivity syndrome (AIS), which is typically caused by mutations in the AR gene, although the underlying genetic mechanisms remain unknown in many cases." (PMID 41249932, 2025). "GSFs from individuals with complete androgen insensitivity syndrome, carrying inactivating mutations in the AR gene, showed no reproducible androgen response." (PMID 41249932, 2025). "We used different study groups: individuals with Differences of Sex Development (DSD), including Complete Androgen Insensitivity Syndrome (CAIS) due to mutated androgen receptor (AR), and men with idiopathic nonobstructive azoospermia." (PMID 38212646, 2024). "A multitude of pathologies, encompassing androgen insensitivity syndrome (AIS), various cancers like those of the prostate, breast, ovary, and pancreas, anabolic conditions like osteoporosis and muscle wasting, are intricately linked to aberrant AR expression." (PMID 38334807, 2024). "Therefore, a molecular analysis of sex-determining region Y (SRY) and androgen receptor (AR) genes was made and the results instead led to a definite diagnosis of complete androgen insensitivity syndrome." (PMID 36556938, 2022). "Modulation of this allosteric pathway could provide a new mechanistic explanation for the presence of AR-related diseases such as PCa and the androgen insensitivity syndrome." (PMID 35163481, 2022). "There are several CpG sites that seem to be of importance for AR expression regulation, as shown, for example, in the mutation‐negative androgen insensitivity syndrome." (PMID 35661403, 2022). "In this particular case, the molecular analysis of the androgen receptor (AR) gene showed the presence of a pathogenic mutation, not previously reported, consistent with complete androgen insensitivity syndrome." (PMID 34670306, 2021). "Complete androgen insensitivity syndrome (CAIS) (OMIM# 300068) is an X-linked recessive disorder characterized by mutations of the androgen receptor (AR) that render the receptor completely non-functional and occurs in 1:20,000 to 90,000 neonates." (PMID 34526969, 2021).
androgen insensitivity syndrome (continued). "Moreover, AR mutants in complete androgen insensitivity syndrome (CAIS) tend to have a greater effect on protein stability than in partial androgen insensitive syndrome (PAIS)." (PMID 32694570, 2020). "Furthermore, individuals with complete androgen insensitivity syndrome, who have dysfunctional AR, are reported to show high rates of depression (~ 36% incidence;) and AR is decreased in the PVN of depressed patients." (PMID 32727567, 2020). "AR targets showed variable expression in patients with androgen insensitivity syndrome." (PMID 31350272, 2019). "This failure of virilization can be either complete or partial depending on the amount of residual androgen receptor function, the partial androgen insensitivity syndrome ranging from mildly virilized female external genitalia to mildly undervirilized male external genitalia." (PMID 28611373, 2017). "Furthermore, the risk of SE is high in patients with androgen-insensitivity syndrome (AIS), a condition associated with aberrant repression of the AR signal due to loss-of-function mutations in the AR gene." (PMID 27144435, 2016). "Its importance is highlighted in the androgen insensitivity syndrome (AIS), a virtual human AR "knock-out" due to inactivating mutations of the AR gene, and characterized by defects in virilization of 46, XY individuals despite normal or elevated serum testosterone levels." (PMID 17945006, 2007). "Androgen insensitivity syndrome (AIS) is a major disorder of sex development (DSD), caused by mutations in the Androgen Receptor (AR) gene in patients with XY-karyotype, leading to tissue resistance to androgens even since the intrauterine life." (PMID 40304984, 2025). "Genetic variants in receptor for T and DHT, AR also cause DSD at a rate of 1 in 99,000 births, termed androgen insensitivity syndrome (AIS)." (PMID 39081229, 2025). "Besides, one patient without AR mutation was clinically diagnosed with complete androgen insensitivity syndrome (CAIS)." (PMID 40247401, 2025). "Although the function of these alternative AR transcripts in the human physiology is not completely understood, these variants have been related to pathological conditions such as prostate cancer (PCa) and androgen insensitivity syndrome (AIS)." (PMID 33273918, 2020). "Indeed, it is clear that the neurologic symptoms of SBMA are not caused by a loss of AR function, as these are not observed in patients with complete androgen insensitivity syndrome." (PMID 31686397, 2019). "Too low AR-activity on the other hand can cause the monogenic condition androgen insensitivity syndrome (AIS), defined by the inability of the androgen receptor to properly respond to androgens i.e. DHT." (PMID 27110943, 2016). "Mutations in the AR have been correlated with a wide spectrum of androgen insensitivity syndromes (AIS), that span from mild androgen insensitivity syndrome (MAIS) and partial androgen insensitivity syndrome (PAIS) to complete androgen insensitivity syndrome (CAIS)." (PMID 25606384, 2014). "Particularly, extended lengths of polyQ repeats within the AR NTD can result in dysfunctional AR and have been identified in patients with androgen insensitivity syndrome, (AIS)." (PMID 21949845, 2011). "The androgen receptor null mouse is one such example, as the elimination of a steroid response element mirrors what we see in some instances of Androgen Insensitivity Syndrome (AIS), thus is an excellent model to understand VSCs and androgen receptor impacts on other systems." (PMID 41357796, 2025). "Aberrant AR function has been detected in various diseases, including AGA, cancer, hypogonadism, androgen insensitivity syndrome, muscle atrophy, and osteoporosis." (PMID 37496996, 2023). "Androgen insensitivity syndrome (AIS) in humans is caused by a defect in androgen synthesis or a mutation in the androgen receptor (AR) gene and causes the level of AMH to not decrease during puberty." (PMID 36982948, 2023).
androgen insensitivity syndrome (continued). "The 5′ UTR variant c.-547C > T in the AR gene was identified in patients with complete androgen insensitivity syndrome (AIS; OMIM: #300068) using SR-GS after negative results by the Sanger sequencing of the gene coding region." (PMID 36672937, 2023). "GFs from 169 individuals were studied encompassing control males (n = 68), molecular defined DSD other than androgen insensitivity syndrome (AIS; n = 18), AR mutation-positive AIS (n = 37), and previously undiagnosed DSD including patients with a clinical suspicion of AIS (n = 46)." (PMID 27583472, 2016). "Genetic alterations in the X-linked androgen receptor (AR) gene are associated with spinal and bulbar muscular atrophy (SBMA, Kennedy’s disease), an adult-onset neuromuscular disease, androgen insensitivity syndrome (AIS), and prostate cancer." (PMID 23720649, 2013). "In adult patients with Sertoli-cells-only syndrome (SCOS) and androgen insensitivity syndrome (AIS), high level of AMH expression is detected in Sertoli cells due to defect of androgen/AR signaling." (PMID 24098470, 2013). "Functionally impaired AR results in androgen insensitivity syndrome (AIS)." (PMID 21048966, 2010). "When looking at data from complete or partial androgen insensitivity syndromes, it is clear that AR expression and AR function are not interchangeable." (PMID 41596366, 2026). "Complete androgen insensitivity syndrome (CAIS) is an uncommon disorder of sexual differentiation in which a genetically male (46,XY) individual presents with a typical female phenotype due to androgen receptor resistance." (PMID 41658711, 2026). "Androgens are essential for male genital differentiation, as demonstrated by individuals with androgen insensitivity syndrome, who often exhibit reduced or absent genital virilization at birth due to reduced or absent AR activity." (PMID 41249932, 2025). "Here, we describe a patient suffering from partial androgen insensitivity syndrome (PAIS) and lacking AR mutations." (PMID 33182400, 2020). "A raised LH and T level may be a clue to the diagnosis of androgen insensitivity syndrome, and although the absolute values of these markers were not remarkable in the current study, the T:LH ratio was higher at first presentation in the cases with an AR mutation." (PMID 27403927, 2016). "Recently, some authors have reported heterozygous loss-of-function NR5A1 mutations in patients with clinical features of androgen insensitivity syndrome (AIS) and apparently normal Leydig and Sertoli cell function but without mutations in the androgen receptor gene (AR)." (PMID 24405868, 2014). "Complete androgen insensitivity syndrome (due to lack of AR function) presents with a female habitus and physiology, including the developmental brain pattern - in spite of internalised testes that secrete normal levels of testosterone." (PMID 23940781, 2013). "Due to the nature of the samples, a direct effect of AR signaling could not be determined; however, future studies using patients undergoing gender affirming care or patients with androgen insensitivity syndrome could provide this information." (PMID 39404231, 2024). "Similarly, immunohistochemical staining revealed high AMH expression in male mice lacking AR in their Sertoli cells, and human patients with androgen insensitivity syndrome (AIS) showed abnormally high levels of AMH." (PMID 24098470, 2013). "As an example, in the Androgen Insensitivity Syndrome (AIS), the testis present in XY individuals produces testosterone but cannot transduce its signal due to the lack of a functional AR." (PMID 37296608, 2023). "Observational studies and case reports in patients with androgen insensitivity syndrome (AIS), where there is a partial or complete lack of androgen receptor signaling, have demonstrated reduced BMD in people with AIS, particularly in the lumbar spine and regardless of estrogen replacement." (PMID 28408926, 2017).